RORC (RAR related orphan receptor C)
Description:
Nuclear receptor that binds DNA as a monomer to ROR response elements (RORE) containing a single core motif half-site 5'-AGGTCA-3' preceded by a short A-T-rich sequence. Key regulator of cellular differentiation, immunity, peripheral circadian rhythm as well as lipid, steroid, xenobiotics and glucose metabolism. Considered to have intrinsic transcriptional activity, have some natural ligands like oxysterols that act as agonists (25-hydroxycholesterol) or inverse agonists (7-oxygenated sterols), enhancing or repressing the transcriptional activity, respectively. Recruits distinct combinations of cofactors to target gene regulatory regions to modulate their transcriptional expression, depending on the tissue, time and promoter contexts. Regulates the circadian expression of clock genes such as CRY1, BMAL1 and NR1D1 in peripheral tissues and in a tissue-selective manner. Competes with NR1D1 for binding to their shared DNA response element on some clock genes such as BMAL1, CRY1 and NR1D1 itself, resulting in NR1D1-mediated repression or RORC-mediated activation of the expression, leading to the circadian pattern of clock genes expression. Therefore influences the period length and stability of the clock. Involved in the regulation of the rhythmic expression of genes involved in glucose and lipid metabolism, including PLIN2 and AVPR1A. Negative regulator of adipocyte differentiation through the regulation of early phase genes expression, such as MMP3. Controls adipogenesis as well as adipocyte size and modulates insulin sensitivity in obesity. In liver, has specific and redundant functions with RORA as positive or negative modulator of expression of genes encoding phase I and Phase II proteins involved in the metabolism of lipids, steroids and xenobiotics, such as SULT1E1. Also plays a role in the regulation of hepatocyte glucose metabolism through the regulation of G6PC1 and PCK1. Regulates the rhythmic expression of PROX1 and promotes its nuclear localization. Plays an indispensable role in the induction of IFN-gamma dependent anti-mycobacterial systemic immunity. [Isoform 2]: Nuclear receptor essential for thymopoiesis and the development of several secondary lymphoid tissues, including lymph nodes and Peyer's patches. Required for the generation of LTi (lymphoid tissue inducer) cells (By similarity). Regulates thymocyte survival through DNA-binding on ROREs of target gene promoter regions and recruitment of coactivaros via the AF-2 (By similarity). Also plays a key role, downstream of IL6 and TGFB and synergistically with RORA, for lineage specification of uncommitted CD4(+) T-helper (T(H)) cells into T(H)17 cells, antagonizing the T(H)1 program. Probably regulates IL17 and IL17F expression on T(H) by binding to the essential enhancer conserved non-coding sequence 2 (CNS2) in the IL17-IL17F locus. Plays a key role in tolerance to gut microbiota and foreign antigens in food by mediating differentiation of peripherally-induced regulatory T-cells (pTreg), which suppress inflammatory responses to commensal microorganisms and food proteins (By similarity). Specifically expressed in antigen-presenting cell populations, such as (1) type 3 innate lymphoid cells (ILC3s), which are required for tolerance to gut microbiota, (2) Thetis cells, also named Janus cells, which are enriched in gut lymph nodes during early life and are required for oral tolerance, and (3) a subset of dendritic cells (By similarity). Following activation by an unknown ligand in antigen-presenting cells, promotes recruitment of transcription regulators, such as PRDM16 or ZBTB46, and drives differentiation of pTreg cells, which maintain immune tolerance and prevent autoimmune diseases (By similarity). May also play a role in the pre-TCR activation cascade leading to the maturation of alpha/beta T-cells and may participate in the regulation of DNA accessibility in the TCR-J(alpha) locus (By similarity).
Synonyms: NR1F3; RORG; RZRG; TOR; IMD42; RZR-GAMMA
Tractability: Small molecule: a drug acting on it is in phase 1 trials; a structure with a bound ligand is known; a high-quality ligand is known; it has a high-quality binding pocket; it belongs to a druggable protein family. PROTAC: ubiquitination databases record sites on it; a small molecule that binds it is known.
Target class: Nuclear hormone receptor subfamily 1 group F member 3; Nuclear hormone receptor subfamily 1; Nuclear receptor; Nuclear hormone receptor subfamily 1 group F; Transcription factor
Chemical probes: JNJ-54119936 (high quality), ML-209, SR2211, Vimirogant (high quality)
Gene: Protein-coding gene on chromosome 1 (151,806,071 to 151,831,845, reverse strand). Ensembl gene ENSG00000143365.
Subcellular location: Nucleus
Subcellular location (Human Protein Atlas): Nuclear bodies
Pathways (Reactome):
Circadian clock: Expression of BMAL (ARNTL), CLOCK, and NPAS2; Phosphorylated BMAL1:CLOCK (ARNTL:CLOCK) activates expression of core clock genes; RORA,B,C and NR1D1 (REV-ERBA) regulate gene expression
Gene expression (Transcription): Nuclear Receptor transcription pathway; RUNX3 Regulates Immune Response and Cell Migration
Immune System: Interleukin-4 and Interleukin-13 signaling
Gene Ontology:
Molecular function: DNA-binding transcription repressor activity, RNA polymerase II-specific; ligand-modulated transcription factor activity; oxysterol binding; protein binding; RNA polymerase II cis-regulatory region sequence-specific DNA binding; sequence-specific double-stranded DNA binding; DNA-binding transcription factor activity; DNA-binding transcription factor activity, RNA polymerase II-specific; nuclear receptor activity; DNA binding; sequence-specific DNA binding; zinc ion binding
Biological process: cellular response to sterol; negative regulation of transcription by RNA polymerase II; adipose tissue development; circadian regulation of gene expression; positive regulation of circadian rhythm; positive regulation of DNA-templated transcription; regulation of fat cell differentiation; regulation of glucose metabolic process; regulation of steroid metabolic process; regulation of transcription by RNA polymerase II; T-helper 17 cell differentiation; xenobiotic metabolic process; intracellular receptor signaling pathway; regulation of DNA-templated transcription; regulation of gene expression
Cellular component: nuclear body; nucleus; chromatin; nucleoplasm
Genetic constraint (gnomAD): Loss-of-function variants: 12 observed, 55.36 expected, observed/expected ratio (o/e) 0.22, 90% interval 0.14 to 0.35. The upper end of that interval is the gene's LOEUF score, 0.35, which puts it in group 1 of 6, group 1 being the genes least tolerant of losing a copy. Missense variants: 444 observed, 645.42 expected, observed/expected ratio (o/e) 0.69, 90% interval 0.64 to 0.74. Synonymous variants: 269 observed, 252.37 expected, observed/expected ratio (o/e) 1.07, 90% interval 0.96 to 1.18.
Homologues: Orthologues: macaque RORC (99% identical), chimpanzee RORC (95% identical), pig RORC (92% identical), rabbit RORC (90% identical), mouse Rorc (88% identical), guinea pig RORC (88% identical), rat Rorc (86% identical), dog RORC (85% identical), tropical clawed frog rorc (32% identical), Caenorhabditis elegans nhr-23 (30% identical), zebrafish rorc (22% identical), Caenorhabditis elegans sex-1 (22% identical), and 183 more. Paralogues in human: RORA (49% identical), RORB (46% identical), NR1D2 (27% identical), NR1D1 (27% identical), RARB (26% identical), RARG (25% identical), RARA (25% identical), THRB (23% identical), PPARG (22% identical), NR1H4 (21% identical), PPARD (21% identical), THRA (21% identical), and 6 more.
Diseases named in the same sentence as RORC in open-access papers:
RORC is named in the same sentence as 111 diseases in open-access papers, as found by Europe PMC text mining. Sharing a sentence is not in itself a finding about the gene and the disease. The quoted sentences say what the papers report.
breast carcinoma (17 papers, 2013 to 2025). "The high expression of RORC is associated with better survival in many types of cancer, such as breast carcinoma, esophageal adenocarcinoma, kidney renal clear cell carcinoma, hepatocellular liver carcinoma, and lung adenocarcinoma in TCGA." (PMID 35459193, 2022). "In addition, RORC protein plays a role in the expression of some clock genes and its expression has been linked to breast cancer survival outcomes." (PMID 32300557, 2020). "Interestingly, both somatic missense mutations and gene amplification in RORC are highly recurrent in breast cancers, being detected in up to 12% of patients." (PMID 32300557, 2020). "Studies using the gene set analysis method confirmed an association with ARNTL, CLOCK, and RORA and additionally reported an association with RORB, RORC, CRY, and the overall pathway in relation to breast cancer risk." (PMID 40534841, 2025). "An RORC agonist suppresses breast cancer cell viability, migration, the EMT transition (microsphere outgrowth) and mammosphere-growth." (PMID 33790307, 2021). "RORC plays a crucial role in the immune system and may affect the tumor immune microenvironment of breast cancer by modulating immune cell functions." (PMID 40969325, 2025). "Furthermore, TCGA database analysis showed a significant correlation of NFKBIA and RORC expression in breast cancer, suggesting a regulatory role of RORs in IκBα transcription regulation." (PMID 35440077, 2022). "RORC overexpression seems to increase distant metastasis-free survival in breast cancer patients." (PMID 32300557, 2020). "The expression level of the RORC and STAT3 was significantly decreased in breast cancer tissues compared to control samples." (PMID 29299026, 2017). "RORC, a member of ROR subfamily, has been studied in various cancer cells and their corresponding tumor microenvironment in recent years, with results showing that it might possess effective prognostic value in both lung and breast cancers." (PMID 37430202, 2023). "In breast cancer cell lines, RORC was shown to repress TGF-β/EMT-signalling and cancerogenic pathways, which indicates that, also in Cyp51 KO mice, decreased activity of RORC could contribute to increased TGF-β/EMT signalling." (PMID 33182326, 2020).
psoriasis (13 papers, 2019 to 2024). An autoimmune condition characterized by red, well-delineated plaques with silvery scales that are usually on the extensor surfaces and scalp. "Mice with TPA-induced psoriasis showed increased gene expression of both the Th17 transcription factor, RORC, and Th17-produced cytokines, Il17a, Il17e, Il17f, and Il22, in the ear tissue compared with those in normal mice." (PMID 39765869, 2024). "Inhibition of BET proteins has been shown to decrease the expression of RORC, IL-17A and IL-22, all of them important psoriasis pro-inflammatory factors, representing a potential new therapy for psoriasis." (PMID 37628670, 2023). "Many studies have shown that the expression of RORC is increased in autoimmune diseases such as MS, RA, psoriasis and Crohn's disease." (PMID 35266286, 2022). "Compared with severe psoriasis, mild psoriasis was characterized by higher IL-17A expression in psoriatic lesion, which is consistent with the alteration of RORC in our study." (PMID 33681365, 2021). "In mice T-cells and dendritic cells had increased STAT3/RORC expression and patients with psoriasis had elevated level of RORC (RORG-t isoform)." (PMID 34445309, 2021). "While the prominent role of RORC in psoriasis as the major controller of Th17 cell differentiation is well described, however, the evidence of RORC expression in psoriasis is controversial." (PMID 34445309, 2021). "In a study published in 2018, the authors determined the mRNA expression level of RORC in patients with psoriasis and found significantly higher gene expression of RORC in patients with psoriasis than in control patients, thus concluding that Th-17 plays a role in the pathogenesis of the disease." (PMID 34067151, 2021). "Further analysis found that RORC and S100A12 were associated with psoriasis severity." (PMID 33681365, 2021). "In a study published in 2018, the authors determined the mRNA expression level of RORC in patients with psoriasis and found significantly higher gene expression of RORC in patients with psoriasis than in controls, thus concluding that Th-17 plays a role in the pathogenesis of the disease." (PMID 30744173, 2019). "PPAR-γ inhibits the transcription of IL-17 by inhibiting its direct transcription factors RORC and STAT3, while FRA-1 can regulate the expression of STATA3, RORC and IL-17 by directly inhibiting PPARγ, thus regulating the development of psoriasis." (PMID 36032067, 2022). "The pathways associated with the ubiquitination-proteasome system were significantly regulated by RORC and S100A12 alteration in psoriasis." (PMID 33681365, 2021). "Moreover, AOA decreased IL-17A, RORC, and IL-22 secretion by Th17 cells, confirming that AOA is effective in the immune regulation of psoriasis." (PMID 37649889, 2023). "In addition, AOA treatment significantly decreased the expression levels of Il17a, RAR related orphan receptor C (Rorc), and IL22 in ear skin of the psoriasis-like mouse model." (PMID 37649889, 2023). "This suggests that the expression of RORC and S100A12 might be regulated by ubiquitination, which is related to the modulation of psoriasis severity." (PMID 33681365, 2021). "Moreover, the following genes were upregulated in CD3+ T cells of psoriasis patients—IL17 (105.2 ± 11.01), STAT3 (6.98 ± 1.96), RORC gene in 15.52 ± 2.18, and FOSL1 (5.79 ± 0.99)." (PMID 34445309, 2021). "Experimental data we obtained support our model and the hypothesis that in psoriasis low level of PPARγ activity stimulates IL17 synthesis because STAT3 and RORC became less suppressed." (PMID 34445309, 2021). "We hypothesize that the expression of IL17, STAT3, FOXP3, and RORC and FOSL1 genes in psoriatic skin is correlated with the level of PPARγ expression, and they belong to the same signaling pathway that regulates the development of psoriasis lesion." (PMID 33133175, 2020).
autoimmune disease (12 papers, 2016 to 2025). A disorder resulting from loss of function or tissue destruction of an organ or multiple organs, arising from humoral or cellular immune responses of the individual to their own tissue constituents. "RORC is a protein-coding gene that regulates the polarization and function of Th17 cells, and is associated with autoimmune diseases and inflammation." (PMID 39295864, 2024). "These qPCR results are consistent with the observed decrease in IFNγ (T‐bet) and IL‐17 (RORC) secretion levels and are particularly interesting as several investigations have associated IL‐21 to autoimmune diseases." (PMID 26762709, 2016). "While skewing of the T cell repertoire is noteworthy, due to the potentially enhanced risk of developing autoimmune disorders and infection, the T cell leukopenia observed in humans carrying RORC biallelic loss of function mutations, is less pronounced than that observed in mice." (PMID 39820614, 2025). "RORC is a critical transcription factor for the generation of pro-inflammatory cytokines, which are closely related to the pathogenesis of autoimmune diseases." (PMID 36941538, 2023). "RORC is required for IL-17A production from Th-17 cells, which plays a crucial role in the pathogenesis of several inflammatory and autoimmune diseases." (PMID 36776357, 2022). "As murine Th17-driven inflammatory disease models were greatly diminished in RORC knock-out mice, this receptor was prioritised as an attractive therapeutic target for the treatment of several autoimmune diseases." (PMID 34673799, 2021). "The observation that Th17-driven inflammatory disease models were greatly attenuated in RORC knock-out mice positioned this receptor as an attractive therapeutic target for the treatment of several autoimmune diseases." (PMID 34673799, 2021). "Alternatively, reducing RA signaling by RORc inhibitors serves as potential therapeutics to combat autoimmune diseases, indicating that RA signaling-based therapies are context-dependent." (PMID 32970669, 2020). "In this study, we observed an elevated TH17 cell frequency as well as elevated RORC- and IL-17A-mRNA expression in peripheral blood of overweight children without allergic asthma, allergic rhinoconjunctivitis, atopic dermatitis, or autoimmune disease." (PMID 29201026, 2017). "Genes relating to certain subsets of T cells that are often connected with autoimmune diseases such as Tregs (FOXP3, CD25) and TH17 (IL-17, RORC) were decreased in gene lists." (PMID 34164359, 2021). "The study also found that people with RR‐MS, who had a positive family history of autoimmune disease, had significantly increased RORC expression compared to people who did not have a positive family history of autoimmune disease." (PMID 35266286, 2022). "We previously tested whether genes coregulated by the “Th17 core” (RORC, STAT3, BATF, IRF4, and MAF) were enriched for gene sets from GWAS of nine autoimmune diseases and three “negative controls” (Alzheimer's, schizophrenia, and type 2 diabetes)." (PMID 30696696, 2019).
COVID-19 (10 papers, 2020 to 2025). A disease caused by infection with severe acute respiratory syndrome coronavirus 2. "Finally, a meta2cell enriched in patients with persistent severe COVID-19 at day 13 (metacell C) contains cells that express hallmark TH17 genes (RORC and CCR6), reflecting a shift toward type III inflammation." (PMID 36973557, 2023). "The top COVID-19 predictor, RORC, is a key regulator of cellular differentiation, immunity and glucose metabolism." (PMID 41279033, 2025). "It was shown that the expression of Th17 cell-associated genes (RORC, IL17A, IL17F, and CCR6) was downmodulated in peripheral blood CD4+ T cells in COVID-19 patients." (PMID 37626620, 2023). "Conversely, during the acute phase of SARS-CoV-2 infection, CD4+ T cells from the lungs of patients with COVID-19 did not increase Th17-associated genes, including RORC, IL17A, and IL17F, and CCR6 expression was significantly reduced in patients with severe COVID-19." (PMID 36146622, 2022). "Both, severe and mild COVID-19 in comparison to controls shared neutrophil-specific CD177 and HP expression among the most upregulated DEGs, as well as lymphocyte-associated genes such as ABLIM1, NELL2, RCAN3, RORC, BACH2, and KLRB1, among the downregulated genes." (PMID 33441124, 2021). "Furthermore, the GWAS of hospitalized COVID-19 identified 3p21.31 locus, wherein the genome-wide significant variant—rs13325613 (chr3:46298373bp; p = 1.17e-08) is a trans-QTL for genes RORA (p = 7.7e-7) and RORC (p = 1.3e-31)." (PMID 34512723, 2021).
lung carcinoma (8 papers, 2018 to 2025). "By directly targeting stigmasterol in lung cancer by RAR-related orphan receptor C (RORC), RORC overexpression reverses the inhibitory effect of stigmasterol on lung cancer." (PMID 38675663, 2024). "This study suggests the functional role of the stigmasterol-RORC axis in lung cancer progression, which provides a potential target for cancer treatment." (PMID 36578938, 2022). "The authors also noted that stigmasterol directly targeted the expression of RORC in lung cancer, and overexpression of RORC reversed the suppressive effect of stigmasterol on cancer cells." (PMID 36578938, 2022). "It was found that overexpression of RORC induces, to some extent, a reversal of the inhibitory activity of stigmasterol on lung cancer cells." (PMID 36290632, 2022). "E.g., the circadian rhythms of ARNTL, RORC and NPAS2 are potentially weak and the circadian rhythm of RORC might also be phase-shifted by several hours in lung cancer." (PMID 39004631, 2024). "For example, with lung cancer subtype-specific meta-analysis, we found consistent downregulation of RAR related orphan receptor C (RORC) in multiple lung SCC studies but not in lung ADC studies." (PMID 30532070, 2019).